MMP14 (matrix metallopeptidase 14)
Diseases named in the same sentence as MMP14 in open-access papers (continued):
Sharing a sentence is not in itself a finding about the gene and the disease.
tumor (continued). "A significant difference was found in the expression of epithelial and stromal MMP-14 and CD44 between early-stage and advanced-stage patients, MMP-14 being more often expressed in the tumor epithelium in advanced-stage patients than in early-stage patients and less often in the tumor stroma." (PMID 27590006, 2016). "As MMP14 is tethered to the cell surface and therefore is restricted to the proximal microenvironment, increased secretion of MMP1 by oncogenic cells may provide a mechanism to regulate cells and ECM proteins at sites distal to the developing tumour." (PMID 27324842, 2016). "MMP-14 is important within the MMP family, for its ability to activate other members, including the cell-surface expressed MMP-2, which may be critically involved in accelerating malignant processes, such as tumor metastasis." (PMID 24765144, 2014). "We found that the expressions of MMP-14, MMP-19 and MMP-2 were upregulated in BCL individuals compared to CC, during which fibroblasts and myeloid cells displayed abundant MMP expression, indicating that the MMPs gene set could participate in inhibits tumor progression of CC." (PMID 39247608, 2024). "MMP-14 present in the peripheral blood correlated positively and significantly with the level of MMP-14 found in tumor secretions obtained from the same patients (rho = 0.58, P = 0.02), suggesting that plasma MMP-14 levels may be used as a surrogate marker for tumor-secreted MMP-14." (PMID 32848608, 2020). "For SAS cells, the gene expression of MMP2, MMP9 and MMP14 in ALG-CS was significantly higher than that in ALG (for MMP2 P = 0, for MMP9 P = 0.04634, for MMP14 P = 0.00194), which indicated that ALG-CS could further enhance MMP gene expression in tumor cells compared with ALG." (PMID 27432752, 2016). "In addition to degrading the collagen surrounding new vascular cells, MMP14 releases latent TGF-β1 from latent TGF-binding protein (LTBP) and activates other MMPs secreted to the medium, such as MMP2, which has a critical role downstream of MMP14 for angiogenesis-mediated tumor invasion." (PMID 26850053, 2016). "The present study demonstrated that low expression of semaphorin-3A and high expression of MMP-14 in NSCLC may promote tumor progression, possibly due to negative synergy, and the combined detection of semaphorin-3A and MMP-14 postoperatively was valuable in the judgment of prognosis." (PMID 24765144, 2014). "Specifically, the non-competitive inhibition of MMP2, MMP14 and MMP13 using potassium ferricyanide has shown in some studies significant reductions in tumor growth in a murine model of breast cancer lung metastases with VCO growth." (PMID 38255995, 2024). "In particular, C3aR1, C5aR1, MMP-14, THBS1, and TREM2 were abnormally highly expressed in orthotopic tumor tissue but were not expressed in lymph node metastasis-negative tissues." (PMID 37744272, 2023). "Moreover, in one of our approaches, MMP14 expression in tumour nests could be used for ENE prediction in biopsies without stroma; this is an extremely important feature as OSCC biopsy specimens often lack connective tissues, as suggested by the analysis of patient prognoses." (PMID 36765296, 2023). "All neoplasms expressed MMP-2, MMP-9, MMP-14 and TIMP-1 independent of the infection state but displayed a variable distribution and intensity as demonstrated by immunohistochemistry." (PMID 33808256, 2021). "Since MMP-14 is abundant in GBM and not normal brain 13, 16-19, CLIO-ICT provides highly specific destruction of tumor vasculature and highly specific elimination of GBM tumor cells and GICs residing in the perivascular niche." (PMID 31723547, 2019). "Weak cytoplasmic staining for Src and MMP14 was observed in the basal cells, but was not present in the stratified layers of normal epithelium in the HPV positive and negative tumour sections." (PMID 26001294, 2017).
tumor (continued). "The experimental results demonstrated that there is a negative correlation between semaphorin-3A and MMP-14 expression in NSCLC, suggesting that these protein levels have negative synergy and promote tumor progression in a collaborative manner." (PMID 24765144, 2014). "In a first step, the BM of an existing vessel is degraded by MMPs that are expressed by ECs, such as MMP-1, MMP-2, MMP-9, and MT1-MMP/MMP14, at which MMP-9 is required for tumor vasculogenesis rather than angiogenesis." (PMID 21941547, 2012). "Of note, we identified TANs as a major but not the only source of MMP14 and OPN in the tumor microenvironment, and TAN specific contribution compared with contributions of other cells, including ECs or TAMs, remains to be determined using cell-specific knockout approaches." (PMID 38329810, 2024). "In PTMC tumor tissues, compared with the nonmetastasis group, the expression of hsa_circRNA_000121, hsa_circRNA_004183, SRC, and MMP-14 increased significantly in the metastasis group (P < 0.05)." (PMID 35891968, 2022). "Finally, the specificity of the PA-L1 protein variant to be cleaved and therefore activated by proteases other than its intended targets (MMP2, MMP9, and MMP14) and deliver 111In-LFE687A to tumor cells was not evaluated here." (PMID 30954944, 2019). "However, MMP14 is up-regulated in both HPV positive and negative tumours suggesting that this pathway is active in both types of cancer." (PMID 26001294, 2017). "Further, levels of related MMPs including MMP1, MMP8, MMP14, MMP2 and MMP9 which have previously been shown to affect tumor cell invasion were not evaluated in these studies and could compensate for MMP13 levels." (PMID 25880591, 2015).
cancer (597 papers, 1999 to 2026). A tumor composed of atypical neoplastic, often pleomorphic cells that invade other tissues. "Beyond dystrophic conditions, MMP2 and MMP14 have been implicated in cardiac fibrosis and muscle remodeling associated with cancer cachexia." (PMID 40966415, 2025). "Matrix metalloproteinase 14 (MMP14) is overexpressed in various cancers and is linked to a bad PC prognosis." (PMID 37670975, 2023). "We tested the predictions that cancer cell matrix protease function was linked to width of invasion strands by generating A431 cancer cells that either over-expressed MMP14, the major collagen protease, or had it deleted via Crispr/Cas9 editing methods." (PMID 36892272, 2023). "In cases of human cancer, there is an overproduction and activation of MMP-14, which has been associated with the invasion and metastasis of cancer cells." (PMID 37513440, 2023). "The researchers found that cytoplasmic ZO-1 improved cancer cell invasive ability through enhancing the expression of matrix metalloproteinase 14 (MMP14/MT1-MMP), which was associated with activated the β-catenin signaling pathway." (PMID 37564207, 2023). "To summarize, these findings suggest that altered glycosylation of several distinct metastasis-associated glycoproteins, including integrins, EGFR, and MMP-14, is a key to the highly invasive cancer cell phenotype." (PMID 35028012, 2022). "In particular, MMP-14 plays a crucial role in vessel maturation and angiogenesis associated with cancer progression." (PMID 36741729, 2022). "Increased expression of membrane type 1-matrix metalloproteinase (MT1-MMP/MMP14) is associated with the development of many cancers." (PMID 35350840, 2022). "The exosome-activated mCAFs upregulate the activity of genes for MMP-1, MMP-2, MMP-7, MMP-8, MMP-13 and MMP-14 that are associated with cancer growth and progression." (PMID 34837514, 2022). "According to previous research, MMP14 was regarded as a potential diagnostic or prognostic marker in multiple types of cancer." (PMID 34638754, 2021). "The expression of MMP14 is associated with immune checkpoint genes in endemic cancer, and these results provide further evidence that MMP14 expression is associated with the level of immune invasion." (PMID 34604053, 2021). "Among the six known membrane anchored matrix metalloproteinases, membrane type I matrix metalloproteinase MT1-MMP (MMP-14) is highly associated with cancer progression, angiogenesis, and immune response." (PMID 34055644, 2021). "At the same time, we found that overexpression of MMP14 was associated with poorer outcomes in a variety of cancers (OS, DSS, PFI, and DFI)." (PMID 34604053, 2021). "In cancer progression, as in physiological developmental processes, a deficiency in MMP-14 cannot be compensated for by other MMPs." (PMID 35008569, 2021). "Epithelial-mesenchymal transition (EMT) is characterised by increased levels of snail, MMP14, cadherin-11 and vimentin and is associated with cancer invasion and metastasis." (PMID 32694700, 2020). "MMPs play significant roles in nearly every hallmark of cancer and many members, including MMP-14, have been investigated as potential diagnostic and prognostic biomarkers." (PMID 32848608, 2020). "As a consequence, we found cancer stem cell-associated proteins, such as mmp2, mmp9, mmp13, mmp14, paxillin, Ras, src and c-myc, as well as genes expressed in the immune system, such as C5, C9, and HMGB1." (PMID 31832023, 2019). "CAIX also associates with MMP14, a key player in the matrix degradation process required for successful invasion by cancer cells." (PMID 29517989, 2018). "Other cancer-associated genes such as Top2a, Ptn, Ptk7, Tnc and Mmp14 were highly expressed in DAKO mice." (PMID 28459858, 2017). "As copper, CD147, MMP-2 and MMP-14 are all implicated to promote the metastasis of cancer, our study sheds light upon their functional mechanisms and relationship in cancer progression." (PMID 28881637, 2017).
cancer (continued). "MMP14 has been implicated in cancer cell invasion and embryonic development because of its ability to degrade extracellular matrix (ECM) macromolecules especially type I collagen." (PMID 26390284, 2015). "Metalloproteases linked to cancer invasion (Mmp14 (MT1-Mmp); Mmp2) and regulators of epithelial mesenchymal transition were upregulated in mlt, and their inhibition rescued the mutant phenotype, thus linking mlt to established models of cell invasion." (PMID 22973180, 2012). "For example, cleavage of CD44 by MMP-14 results in increased motility in different cancer cell lines and mutation of the putative MMP-14 cleavage site in CD44 inhibits migration." (PMID 14612884, 2003). "Additionally, EphB4 knockout cells had increased expression of matrix metallopeptidase 14, pinin, and keratins 7, 8, 16, and 20, genes associated with increased proliferation, and metastasis across multiple cancer types." (PMID 39489818, 2025). "Additionally, there are several aME genes whose dysregulation is associated with cancers when misregulated, such as Mmp14, Nid1, Mdm2, Cd36, and Id3." (PMID 41223055, 2025). "The presence of MMP-14 has been linked to unfavorable outcomes in patients suffering from a variety of cancers, including melanoma; advanced neuroblastoma; mesothelioma; lung cancer; tongue, head, and neck carcinoma; and bladder, breast, ovarian, pancreatic and colorectal cancers." (PMID 37513440, 2023). "To validate in the high‐risk group patients, cancer cells may have the more progression ability than the low‐risk group, we performed trans‐well assay by controlled the risk scores parameter MMP14 and INHBA." (PMID 35150061, 2022). "In different types of cancer, expression and activity of MMP14 were associated with poor prognosis." (PMID 33924099, 2021). "Upon binding to MMP-14, it is taken up by cancer cells and causes them to die." (PMID 35008569, 2021). "Furthermore, MMP14 is attributed as one of the main MT-MMPs implemented in activating cancer associated proMMP2." (PMID 32575583, 2020). "Strikingly, transgenic mice that overexpress MMP-3, MMP-7 or MMP-14 give rise to spontaneous mammary hyperplasias and malignancies supporting a causal role for MMPs in cancer development." (PMID 14612884, 2003). "This validated the biological relevance of our tissue models and newsECM profiling, as MMP-14 has reported activities to digest basement membrane components such as Collagens and Laminins, and its overexpression is frequently associated with cancer migration and metastasis." (PMID 40166338, 2025). "Moreover, binding sites for the activating transcription factors HIF-2α, Egr1, SP1, as well as E2F1, -3 and -5 have been found within the MMP-14 promoter, all of which are associated with increased malignancy in the context of various cancers (and references therein)." (PMID 33379400, 2020). "Taken together, these data suggest that the localization and association of CAIX and MMP14 may lead to MMP14 activation at invadopodia, providing a novel mechanism of invasion that can be incorporated into the arsenal of functional processes used by cancer cells for invasion and metastasis." (PMID 29517989, 2018). "These considerations suggest that MMP-14 occupies a complex role in cancer biology, acting as both a driver of genomic instability during early transformation and a support for genome maintenance in established tumors." (PMID 41542511, 2026). "MMP14 raised in several types of cancer, promote angiogenesis, inflammation, cancer cell invasion and metastasis." (PMID 40407957, 2025). "We employed a panel of six fluorescently labeled CCP probes that were designed for cleavage by specific proteases implicated in cancer progression: ACE2, CATB, METAP1/2, MMP14, plasmin, and USP1516–22." (PMID 40890441, 2025).
cancer (continued). "MMP-14 (MT1-MMP) has also been suggested as a great candidate for anti-cancer treatment, due to the significant involvement in migration and invasion." (PMID 41228294, 2025). "Recently, MMP-14 (MT1-MMP) was reported to be up-regulated in some types of cancer and to promote cancer cell invasion and metastasis." (PMID 40075856, 2025). "Despite the well-established significance of MMP14 in cancer, the regulatory mechanisms and functions of MSC-derived MMP14 in AML remain largely unexplored." (PMID 40121502, 2025). "Our analysis revealed a notable increase in MMP14 mRNA levels across various cancer types, including BLCA and COAD, among others." (PMID 40352589, 2025). "The behaviors of CD59 and MMP14 after irradiation have mainly been investigated in cancer cells because of the wide application of IR in this field." (PMID 41516288, 2025). "CXCR4+ cancer stem cells also show increased tumor invasion and cell migration, via the activation of Rac1 and MMP-2/MMP-14 proteinases and enhanced angiogenesis by triggering cancer cell adhesion to endothelial cells and upregulation of VEGF/VEGFR." (PMID 40307933, 2025). "Collectively, these results show that cells with high integrin-RhoA/YAP activity and MMP14 function act as leaders that drive microchannel network construction, while coinhibiting either pathway significantly inhibits cancer metastasis." (PMID 41417886, 2025). "Based on the interaction network generated through the STRING database, the functional relevance of MMP-9 and MMP-14 in cancer cell behavior was clearly demonstrated." (PMID 40867236, 2025). "MMP14 is highly expressed in various tumors, promoting inflammation, angiogenesis, cancer cell invasion and metastasis, and drug resistance." (PMID 40121502, 2025). "The MMP-14 is the driving force behind the ECM destruction during cancer invasion, and metastasis also influences both intercellular and cell–matrix communication by regulating the activity of several plasma-membrane-anchored and extracellular proteins." (PMID 39199663, 2024). "It is worth noting that the highest content was demonstrated in both control tissues for MMP-14, while a very similar amount of both enzymes was found in both grades of cancer." (PMID 39125675, 2024). "Earlier studies have shown that upregulation of specific MMP, such as MMP-14 (MT1-MMP), is associated with poor prognosis in cancer patients." (PMID 39062015, 2024). "MMP-14, also known as MT1-MMP, is a Membrane-type Metalloproteinase expressed on fibroblasts and cancer cells." (PMID 38361931, 2024). "Our further analysis of immune cell content revealed a positive correlation between MMP14 expression and the infiltration levels of CD8 + T cells, cancer-associated fibroblasts, and macrophages." (PMID 38898429, 2024). "Both control and cancer human kidney tissues contain MMP-14 and MMP-15 enzymes in the form of high-molecular-weight complexes." (PMID 39125675, 2024). "In fact, MMP2 and MMP14 in the conditioned media of mild aggressive cancer cells were strongly activated by SEMA3F, in accordance with previous results that demonstrated that these MMPs are involved in the cleavage of collagen IV, a basal membrane compound." (PMID 39138514, 2024). "Molecularly, this is supported by enhanced MMP14 expression in cancer cells and their low dependence on ECM adhesion to proliferate and migrate." (PMID 37078535, 2024). "Overexpression of the transmembrane matrix metalloproteinase MT1-MMP/MMP14 promotes cancer cell invasion." (PMID 38341434, 2024). "Correlative evidence suggests that high MMP14 expression in cancers is significantly correlated with adverse prognosis, and it was observed that BC patients with high MMP14 expression have a shorter DSS." (PMID 38189813, 2024).